HIF1A (hypoxia inducible factor 1 subunit alpha)
Diseases named in the same sentence as HIF1A in open-access papers (continued):
Sharing a sentence is not in itself a finding about the gene and the disease.
Obesity (continued). "Therefore, it is tempting to think that IL-16 could be promoting the reduction of Hif1a, which causes a decrease in Vegf in the context of altered adipose tissue remodeling in obesity." (PMID 38544694, 2024). "To assess whether improved AT metabolic health caused by adipocyte HIF1α inactivation would have beneficial effects on muscle health in the setting of sarcopenic obesity, we generated a mouse model in which adipocyte Hif1a was inactivated in a doxycycline (DOX)-inducible manner." (PMID 36875847, 2023). "Thus, the use of HIF1α inhibitors should be evaluated with caution as it may increase the risk of obesity-induced inflammatory complications such as psoriasis and rheumatoid arthritis or risk of infections." (PMID 33257753, 2020). "Conversely, n-3 PUFA have been shown to improve the hypoxic AT microenvironment by reducing adipocyte size and to decrease obesity-associated expression of HIF-1α, thereby providing a mechanism through which local leptin signaling responsiveness could be attenuated." (PMID 25360510, 2014). "Western blot analysis revealed that, compared with controls, the protein expression levels of GLUT4 and p-IRS1 were markedly decreased in the obesity group (P < 0.0001), whereas HIF-1α and TNF-α protein levels were significantly increased (P < 0.0001)." (PMID 41505418, 2026). "The human data shows that obesity enhances the activation of the FA/HIF‐1α/CCL2 pathway in tumor tissue and the CCL2/CCR2/PPARα axis in adjacent adipose tissue, thereby accelerating tumor progression and promoting adipolysis in the surrounding adipose tissue." (PMID 41160815, 2026). "Obesity leads to an increased supply of lipids, which in turn raises the expression of HIF‐1α and promotes cancer progression." (PMID 41160815, 2026). "Taken together, these findings suggest that obesity‐induced lipid supply increases HIF‐1α expression in tumors, enhancing CCL2 secretion." (PMID 41160815, 2026). "During the development of obesity, the vascular oxygen supply cannot keep up with the expansion of adipose tissue, leading to local hypoxia and Hif1α activation." (PMID 39693610, 2025). "Overexpression of HIF-1α exacerbates adipose tissue dysfunction by inducing fibrosis and insulin resistance in white adipose tissue, thereby promoting obesity." (PMID 41141252, 2025). "Serpina3c inhibits the Hif1α-glycolysis pathway and reduces de novo lipogenesis and lactic acid secretion in adipocytes by binding to Nrf2, ultimately ameliorating obesity, hypertriglyceridemia, and metaflammation induced by HFD." (PMID 39693610, 2025). "Estrogen suppresses PS gene transcription via ERα, and obesity-related hypoxia stabilizes hepatic HIF1α, which also reduces PS level." (PMID 41243971, 2025). "Obesity-induced hypoxia in adipose tissues activates the expression of hypoxia-inducible factor 1 alpha (HIF-1α), which can stimulate the release of proinflammatory cytokines to induce inflammation." (PMID 40863244, 2025). "This study ultimately demonstrates that Serpina3c interacts with the intracellular binding protein Nrf2 in adipocytes to inhibit the Hif1α-glycolysis axis, thereby alleviating obesity-related hypertriglyceridemia and metabolic inflammation." (PMID 39693610, 2025). "Failure of HIF-2α to exert its inhibitory function allows persistent HIF-1α activation, accelerating the inflammatory response in obesity and contributing to IR development." (PMID 41039626, 2025). "This study intergartes clinical dosing evidence with mechanistic investigation to identify and validate the 3:1 berberine-wogonin ratio as a dual targeting strategy against HIF-1α/HIF-2α pathways, effectively ameliorating obesity-associated insulin resistance." (PMID 41039626, 2025). "In obesity, the tumour-surrounding adipocytes are more prone to activating the HIF-1α/MMP-14 signalling pathway." (PMID 39941741, 2025).
Obesity (continued). "It has also been proposed that, in obesity, metabolic dysregulation activates HIF-1α in adipose tissue macrophages, promoting chronic inflammation and insulin resistance." (PMID 39766314, 2024). "Obesity is also associated with elevated HIF-1α mRNA and protein in adipose tissue, while HIF-1α activation in macrophages is associated with the development of insulin resistance and glucose metabolism in addition to pro-tumour mechanisms." (PMID 39251829, 2024). "HIF1α is a transcription factor that contributes to chronic inflammation in obesity, and its inhibition in adipocytes leads to reduced fibrosis and inflammation in cell and animal models." (PMID 38544694, 2024). "Obesity is accompanied by increased serum leptin levels, which activate hypoxia-inducible factor 1-alpha (HIF-1α)-VEGF signaling in hypothalamic astrocytes, thereby inducing structural remodeling of the glial interface." (PMID 38800473, 2024). "In obesity, HIF-1α contributes to chronic inflammation by promoting the expression of proinflammatory cytokines and recruiting M1 macrophages." (PMID 38247541, 2024). "Given the early occurrence of tissue hypoxia in WAT during diet-induced obesity, a number of studies have demonstrated that HIF-1α in adipocytes can exacerbate insulin resistance and tissue inflammation." (PMID 39473019, 2024). "To investigate how myeloid-specific Hif-1α KO mice were protected from the diet-induced obesity, we examined histology of epididymal white adipose tissue (eWAT)." (PMID 39473019, 2024). "In AF, an up-regulation of the hypoxia-inducible factor (HIF) pathway and an increased expression of hypoxic and angiogenic markers were observed, and the transcription factor HIF-1α is upregulated in the adipose tissue in obesity." (PMID 38247541, 2024). "In conclusion, our study showed that LINK‐A promoted HFD‐induced obesity by reducing thermogenesis through the HB‐EGF‐triggered stabilization of HIF1α." (PMID 38145352, 2024). "At the same time, the deletion of HIF-1α reduced macrophage accumulation and IL-1β production, highlighting its role in regulating metabolic stress and inflammation in obesity." (PMID 39766314, 2024). "In summary, inhibition of LINK‐A using LINK‐A LNAs effectively mitigated the obesity induced by HFD in LINK‐A KI mice by suppressing the activated LINK‐A/HB‐EGF/HIF1α loop." (PMID 38145352, 2024). "Another mechanism of obesity-induced inflammation is the activation of intracellular hypoxia inducible factor 1 alpha (HIF-1α), which in low oxygen conditions, characteristic of obesity, promotes the expression of genes involved in angiogenesis and apoptosis." (PMID 39064298, 2024). "By using myeloid-specific Hif-1α knockout (KO) mice, we observed that these mice were protected from diet-induced obesity and exhibited an improved thermogenic tolerance upon cold challenge." (PMID 39473019, 2024). "Elevated Hif1a in adipose tissue contributes to obesity-related chronic inflammation, insulin resistance, and metabolic dysfunction." (PMID 38029302, 2024). "Both obesity and cancer are linked to hypoxia, which triggers the production of pro-angiogenic factors like VEGF and hypoxia-inducible factor 1 subunit alpha (HIF-1α)." (PMID 38068912, 2023). "In murine models of Western diet-induced obesity, it was found that HIF-1α expression, stabilization and nuclear translocation occurred in CLS-associated macrophages in both SAT (mammary glands) and VAT (mesenteric fat)." (PMID 37233716, 2023). "Genetically modified mice in which Hif1a is constitutively inactivated in Adipoq-expressing mature adipocytes are protected from unhealthy AT remodeling in diet-induced obesity." (PMID 36875847, 2023). "These events raise the possibility that suppression of HIF-1α can prevent fibrotic and inflammatory changes induced by hypoxia or obesity." (PMID 36777361, 2023).
Obesity (continued). "In genetically modified mice exposed to a high-fat diet, interruption of adipocyte HIF1A or ARNT, specifically, has been associated with decreased adipogenesis, prevention of obesity, and decreased instances of insulin resistance." (PMID 37899888, 2023). "There is sustained, abnormal cytoplasmic-nuclear signalling involving membrane tyrosine kinase receptors (TKR), NF-κB activation and hypoxia-inducible factor-1α (HIF-1α) stabilization, as well as many epigenetic modifications in individuals with obesity." (PMID 37233716, 2023). "Increased exposure of ATM to the saturated fatty acid palmitate during high-fat diet-induced obesity further promotes glycolysis, IL-1β release and HIF-1α nuclear translocation under both WAT hypoxia and normoxia." (PMID 37233716, 2023). "In mouse models, suppression of HIF1α activity in mature adipocytes and adipocyte progenitors protects AT from pathologic remodeling and ameliorates metabolic disorders in diet-induced obesity." (PMID 36875847, 2023). "Adipose tissue hypoxia and the activation of HIF-1α in obesity contribute to insulin resistance and type 2 diabetes." (PMID 36777361, 2023). "Here, we utilized a doxycycline-inducible adipocyte Hif1a knockout mice to evaluate the muscle-protective effects of metabolically healthy AT remodeling in the context of co-occurring sarcopenia and obesity." (PMID 36875847, 2023). "It was shown that inflammatory mediator levels increase in obesity and have been shown to regulate HIF1A levels in adipose tissue." (PMID 36230822, 2022). "This ratio was elevated in obesity, hypertension, and autism, and decreased in a Hypoxia Induced Factor 1α (HIF-1α) induced alcoholic liver disease mouse model." (PMID 35719350, 2022). "On the other hand, genes up-regulated with pregravid obesity enriched to GO terms associated with transcriptional regulation (JMJD1C, CHD1, HIF1A, TCF25, and KLF6)." (PMID 33912153, 2021). "To provide a proof-of-concept study, we quantified AT hypoxia by hypoxia inducible factor 1 A (HIF1A) protein abundance in human participants ranging from lean to severly obese (class III obesity)." (PMID 33758342, 2021). "In this study, losartan is involved in dampening obesity-induced proinflammatory gene expression, suppressing the ratio of M1/M2, suggesting that HIF-1α activation plays a prominent role in related macrophage polarization in ob/ob mice." (PMID 34360607, 2021). "The therapeutic effect in obese subjects of EA is the alleviation of obesity-induced inflammation through suppressing HIF-1α signaling and restraining the NF-κB signaling pathway." (PMID 35095910, 2021). "This is contrary to a study, which demonstrated that adipose HIF1A overexpression inhibits thermogenesis and cellular respiration in brown adipose tissue, promoting obesity in the setting of reduced ambient temperature." (PMID 34895148, 2021). "Increased expression of PDK1 and PDK2 by JUN and FOS enforces HIF1a stability to facilitate adipocyte differentiation and obesity." (PMID 34552205, 2021). "Obesity-mediated macrophage M1 activation was also required for HIF-1α expression in the liver and EWAT of ob/ob mice." (PMID 34360607, 2021). "Here, we used ob/ob mice to investigate the relationship between lipotoxic-related IR and HIF1α-related inflammation in obesity model." (PMID 34889901, 2021). "As expected, obesity increased significantly HIF-1α expression in visceral adipose tissue, an effect that was reversed by the exposure of obese animals to CIH." (PMID 34439481, 2021). "Hif1a, a master transcription factor of oxygen homeostasis, induces inflammation and insulin resistance in obesity, targeting mainly adipose tissue." (PMID 33925229, 2021). "With this in mind, we investigated the implications of HIF1α activation in cDCs and its physio-pathological consequences in obesity-induced chronic inflammation." (PMID 33257753, 2020).
Obesity (continued). "As a promoter of obesity, mice overexpressing Hif-1α in adipocytes have elevated obesity and insulin resistance associated with increased inflammation and fibrosis." (PMID 32389123, 2020). "Here we examined the effect of hypoxia-induced transcription factor HIF1α activation on classical dendritic cell (cDCs) function during obesity." (PMID 33257753, 2020). "On the contrary, the disruption of adipose HIF-1α improves insulin sensitivity and decreases adiposity in diet-induced obesity (DIO) mice." (PMID 32752112, 2020). "Although deletion of HIF1α in cDCs results in increased obesity-tissue inflammation, therapeutic treatment with the selective HIF1α inhibitor PX-478 slows down the progression of obesity-induced adipose tissue inflammation." (PMID 33257753, 2020). "To further understand the effects of HIF-1α deletion on macrophage inflammatory status in WAT during obesity, we measured the expression of a panel of markers that characterize alternatively activated macrophages." (PMID 32221369, 2020). "We found that deletion of Hif1α on cDCs results in enhanced adipose-tissue inflammation and atherosclerotic plaque formation in a mouse model of obesity." (PMID 33257753, 2020). "Adipocyte specific Hif-1α or Hif-1β knockout, or inhibition of Hif-1α by inhibitors decrease obesity and insulin resistance in mice fed with high-fat diet." (PMID 32389123, 2020). "The present study was designed to investigate the role of HIF1α activation in cDCs in an experimental model of obesity by using mice with HIF1α deletion specifically in cDCs." (PMID 33257753, 2020). "Collectively, our data identify enhanced glycolysis and HIF-1α activation as drivers of low-grade inflammation in obesity." (PMID 32221369, 2020). "We next tested the effects of macrophage-specific deletion of HIF-1α on obesity related inflammation and metabolic dysfunction." (PMID 32221369, 2020). "Adipose tissue from obese people is characterized by a high expression of HIF-1α, and the activation of HIF-1α induces obesity." (PMID 33027921, 2020). "Next, we used the small interfering RNA (siRNA) method to confirm the role of HIF-1α during the action mechanism of TJT in ameliorating obesity-AD comorbidity." (PMID 31920651, 2019). "Our study showed remarkably high expression of HIF-1α in the HFD/DNFB-induced obesity-AD comorbidity mice model, supporting its involvement in this certain status." (PMID 31920651, 2019). "Impaired adipogenic differentiation during obesity promotes adipocyte hypertrophy and triggers hypoxia responses which result in the induction of the key hypoxia transcription factor HIF1-α." (PMID 31470850, 2019). "To elucidate the role of HIF-1α in the pathogenesis of obesity-AD comorbidity, we established a comorbidity in vitro model." (PMID 31920651, 2019). "In adipocytes, HIF-1α is considered the main mediator of the hypoxic response and involved in the pathophysiological consequences of adipocyte dysfunction during obesity." (PMID 30909461, 2019). "Disruption of HIF-1α function in adipose tissue improves high fat diet–induced obesity and insulin resistance." (PMID 31470850, 2019). "TJT treatment regulated NF-κB-mediated inflammatory signaling by suppressing HIF-1α in the vitro model of obesity-AD comorbidity in a dose-dependent manner." (PMID 31920651, 2019). "This study raises important questions: Are hypoxic conditions and elevated HIF-1α levels during obesity involved in A2 upregulation?" (PMID 30909461, 2019). "HIF-1α, a key regulator of glycolysis, nonetheless appeared to play no critical role in proinflammatory activation of ATMs during early stages of obesity." (PMID 29333574, 2018). "Then we validated 7 obesity or lipid metabolism related genes (Hif1a, Spon1, H19, Adrb2, Vldlr, Zfp36, Smad3), and found that compared to CTL group, Vldlr was hypermethylated and low expressed, and Hif1α was demethylated and high expressed in the VDD group." (PMID 29321608, 2018).
Obesity (continued). "HIF-1α mRNA and protein are enhanced in adipose tissue in a model of diet-induced obesity, by a mechanism that involves adipogenesis, insulin, and hypoxia." (PMID 30443205, 2018). "Diet-induced obesity induces an upregulation of hepatic HIF-1α, as a compensatory mechanism for metabolic regulation." (PMID 30443205, 2018). "Under high‐fat conditions, WT mice gained more weight compared to mice where HIF1α was deleted specifically in white adipose tissue (WAT), indicating a protective role for HIF1α against obesity." (PMID 28984064, 2017). "And the overexpression of HIF-1α led to insulin resistance, adipose tissue inflammation and obesity." (PMID 28496128, 2017). "Fascinatingly, PHD2 inhibition with DMOG ameliorates the skeletal muscle regenerative defects that occur with obesity with a corollary increase in HIF-1α and VEGF levels." (PMID 28725215, 2017). "Recently, we demonstrated that emodin inhibited hepatic HIF-1α expression in the mice that had diet-induced obesity and also showed evidence that the HIF-1α-inhibiting effect of emodin was a result of decreased HIF-1α biosynthesis." (PMID 29152137, 2017). "On the other hand, inhibition of HIF1A in adipose tissue induces obesity and glucose intolerance, due to the impairment of energy expenditure in mice." (PMID 29196658, 2017). "Inhibition of ANT2 and/or HIF-1α can reverse the complications of obesity, for example, insulin resistance." (PMID 28607631, 2017). "Western blotting showed placental hypoxia-inducible factor 1 alpha subunit (HIF1A) protein to be elevated by maternal obesity (Control vs. Obese p = 0.009), and restored to control levels with exercise (Obese vs. Obese-exercised p = 0.034)." (PMID 28291256, 2017). "Other studies have suggested that transgenic or pharmacological inhibition of HIF-1α in adipocytes prevents the onset of obesity from overfeeding and improves insulin sensitivity." (PMID 28725215, 2017). "Hypoxia has a key role in initiating obesity disorders through affecting multiple gene expressions (over 1000 genes) in adipocytes, in particular HIF-1α." (PMID 28607631, 2017). "Increased MG formation by glyceroneogenesis and decreased Glo-1 expression through HIF1α signalling therefore provides the conditions for dicarbonyl stress in obesity." (PMID 27338619, 2016). "The obesity state-induced hypoxia was suggested to be a major stimulator of HIF1α expression and activity." (PMID 26271607, 2015). "A key role for HIF-1α has been proposed in the promotion and maintenance of dietary obesity, at least in part, by suppressing adipocyte lipid catabolism." (PMID 26619907, 2015). "Knockout of PHD2 in adipocytes reduces HFD-induced obesity and improves glucose tolerance in a HIF-1α-dependent manner." (PMID 25546437, 2014). "Diet‐induced obesity can result in hypoxia and induce increases in hypoxia‐inducible factor‐1 alpha (HIF‐1α), a key “oxygen sensing” regulator." (PMID 25347855, 2014). "Here, our results show that obesity increased hypoxic (HIF-1α) and inflammatory responses (TNF-α and NF-κB) in the cochlea of CD/1 mice, especially in the SG and SL." (PMID 23637762, 2013). "The novelty of our study is that we have shown that therapeutic depletion of HIF-1α in severe obesity induces a metabolic switch to fat oxidation resulting in lower metabolic efficiency, energy wasting and weight loss." (PMID 23049707, 2012). "The HIF1A gene is expressed constitutively in some cell types, in others it is upregulated by hypoxia or obesity, although downregulation of mRNA levels by hypoxia has also been reported in human fat cells." (PMID 20175888, 2010). "In type 2-high, type 2-low, and obesity-related asthma endotypes, chronic hypoxia, HIF-1α stabilization, ORMDL3-ceramide signaling, and systemic metabolic stress converge to induce highly glycolytic, Th2/Th17-polarizing DCs in a lactate-rich, acidic microenvironment." (PMID 42004956, 2026).